VPS51 (VPS51 subunit of GARP complex)
Description:
Acts as a component of the GARP complex that is involved in retrograde transport from early and late endosomes to the trans-Golgi network (TGN). The GARP complex is required for the maintenance of protein retrieval from endosomes to the TGN, acid hydrolase sorting, lysosome function, endosomal cholesterol traffic and autophagy. VPS51 participates in retrograde transport of acid hydrolase receptors, likely by promoting tethering and SNARE-dependent fusion of endosome-derived carriers to the TGN. Acts as a component of the EARP complex that is involved in endocytic recycling. The EARP complex associates with Rab4-positive endosomes and promotes recycling of internalized transferrin receptor (TFRC) to the plasma membrane.
Synonyms: ANG2; C11orf2; C11orf3; FFR; ANG3; PCH13
Tractability: PROTAC: ubiquitination databases record sites on it; its protein half-life has been measured.
Gene: Protein-coding gene on chromosome 11 (65,089,324 to 65,111,862, forward strand). Ensembl gene ENSG00000149823.
Subcellular location: Golgi apparatus, trans-Golgi network; Recycling endosome
Subcellular location (Human Protein Atlas): Golgi apparatus; Vesicles; Nucleoli
Pathways (Reactome):
Vesicle-mediated transport: Retrograde transport at the Trans-Golgi-Network
Gene Ontology:
Molecular function: protein binding
Biological process: autophagy; brain morphogenesis; endocytic recycling; lysosomal transport; retrograde transport, endosome to Golgi; Golgi organization; Golgi vesicle transport; protein targeting; vesicle-mediated cholesterol transport
Cellular component: EARP complex; GARP complex; Golgi apparatus; membrane; recycling endosome; trans-Golgi network membrane; cytosol; trans-Golgi network
Genetic constraint (gnomAD): Loss-of-function variants: 55 observed, 53.64 expected, observed/expected ratio (o/e) 1.03, 90% interval 0.82 to 1.28. The upper end of that interval is the gene's LOEUF score, 1.28, which puts it in group 5 of 6, group 1 being the genes least tolerant of losing a copy. Missense variants: 943 observed, 1,007.6 expected, observed/expected ratio (o/e) 0.94, 90% interval 0.89 to 0.99. Synonymous variants: 473 observed, 438.42 expected, observed/expected ratio (o/e) 1.08, 90% interval 1 to 1.16.
Homologues: Orthologues: macaque VPS51 (99% identical), chimpanzee VPS51 (98% identical), dog VPS51 (97% identical), mouse Vps51 (96% identical), rat Vps51 (95% identical), guinea pig VPS51 (95% identical), pig VPS51 (92% identical), rabbit VPS51 (85% identical), tropical clawed frog vps51 (69% identical), zebrafish vps51 (69% identical), Drosophila melanogaster Vps51 (41% identical), Caenorhabditis elegans vps-51 (26% identical).
Diseases named in the same sentence as VPS51 in open-access papers:
VPS51 is named in the same sentence as 12 diseases in open-access papers, as found by Europe PMC text mining. Sharing a sentence is not in itself a finding about the gene and the disease. The quoted sentences say what the papers report.
developmental delay (1 paper, 2025). "In this article, we present two siblings with a novel homozygous variant in VPS51 gene (c.1511C>T; p.Thr504Met), exhibiting developmental delay, thin corpus callosum, severe ID, epilepsy, microcephaly, hearing loss, and dysphagia." (PMID 40565173, 2025). "In this article, we present two siblings with a novel homozygous variant in VPS51 (Vacuolar protein sorting 51) gene (c.1511C>T; p.Thr504Met), exhibiting developmental delay, a thin corpus callosum, severe intellectual disability, epilepsy, microcephaly, hearing loss, and dysphagia." (PMID 40565173, 2025).
emphysema (1 paper, 2021). "The cytosolic transport (RNF126, PLEKHJ1, VPS51, and AP1G1), target of rapamycin (mTOR) signaling (PIK3CA, STK11, RPS6KB2, and PRR5), regulation of translation, metabolic regulation, and apoptosis are involved in the percent emphysema-associated network." (PMID 34777474, 2021).
infection (1 paper, 2021). The state of being infected such as from the introduction of a foreign agent such as serum, vaccine, antigenic substance or organism. "Thus, external application of VPS51+DCTN1+SAC1‐dsRNA inhibits infection of Botrytis cinerea, S. sclerotiorum and A. niger." (PMID 33774895, 2021).
VPS51 also shares sentences with these, for which no sentence is quoted: brain malformations (1 paper); Cerebellar atrophy (1); COVID-19 (1); disseminated candidiasis (1); epilepsy (1); Failure to thrive (1); Intellectual disability (1); liver dysfunction (1); microcephaly (1).